RBM41 (RNA binding motif protein 41)
Description:
May bind RNA.
Synonyms: FLJ11016
Tractability: PROTAC: ubiquitination databases record sites on it.
Gene: Protein-coding gene on chromosome X (107,052,095 to 107,118,823, reverse strand). Ensembl gene ENSG00000089682.
Subcellular location (Human Protein Atlas): Cytosol; Nuclear speckles
Gene Ontology:
Molecular function: protein binding; nucleic acid binding; RNA binding
Cellular component: U12-type spliceosomal complex
Homologues: Orthologues: chimpanzee RBM41 (98% identical), macaque RBM41 (97% identical), pig RBM41 (96% identical), dog RBM41 (95% identical), guinea pig RBM41 (91% identical), mouse Rbm41 (88% identical), rabbit RBM41 (86% identical), rat Rbm41 (84% identical), zebrafish rbm41 (40% identical), Drosophila melanogaster CG44249 (17% identical). Paralogues in human: RNPC3 (21% identical).
Diseases named in the same sentence as RBM41 in open-access papers:
RBM41 is named in the same sentence as 1 disease in open-access papers, as found by Europe PMC text mining. Sharing a sentence is not in itself a finding about the gene and the disease. The quoted sentences say what the papers report.
cerebellar ataxia (1 paper, 2024). A neurological syndrome characterized by clumsy and uncoordinated movement of the limbs, trunk, and cranial muscles. "Furthermore, an 84C > U mutation that compromises the U12 3′-terminal stem-loop integrity leads to early onset cerebellar ataxia due to overtrimming of the 3′-terminal stem-loop which removes the binding site of the U11/U12-65K and RBM41 proteins." (PMID 38499487, 2024).